CYP24A1 (cytochrome P450 family 24 subfamily A member 1)
Diseases named in the same sentence as CYP24A1 in open-access papers (continued):
Sharing a sentence is not in itself a finding about the gene and the disease.
breast carcinoma (continued). "The subgroup analysis showed that low CYP24A1 expression indicated a poor overall survival of patients with basal (P = 0.0049), HER2 (P = 0.044), Lum A (P = 0.11) and Lum B (P = 0.013) breast cancer." (PMID 31548577, 2019). "With regard to the molecular subtype, only basal breast cancer had higher CYP24A1 expression compared to normal tissue, while Lum A, HER2 and Lum B had lower CYP24A1 expression compared to normal tissue." (PMID 31548577, 2019). "Given that CYP24A1 and CXCL14 were the top upregulated genes, we further examined their role in MDA-MB-231 breast cancer cell invasion." (PMID 28003019, 2016). "A fully characterized series of 189 breast carcinomas in situ arranged in 22 TMAs was assessed for the expression patterns of VDR, CYP27B1 and CYP24A1." (PMID 20831823, 2010). "A possible explanation of how vitamin D might affect breast cancer biology might be the tumor suppressive effects of vitamin D receptor catabolism, as a defect in the vitamin D receptor (e.g., CYP27B1 and CYP24A1 regulation) led to decreased signaling." (PMID 36986179, 2023). "In the absence of ligand, the basal mRNA expression of CYP24A1 correlated inversely with VDR protein levels in several breast cancer cell lines and the unliganded VDR exerts a repressive action on CYP24A1." (PMID 33809117, 2021). "Considering the high heterogeneity of vitamin D signaling in breast cancer, it is unknown whether vitamin D resistance through VDR methylation or CYP24A1 amplification during tumor progression would emerge for one individual’s breast cancer." (PMID 31548577, 2019). "Breast cancer with a positive lymph node status had higher CYP24A1 expression than breast cancer with a negative lymph node status." (PMID 31548577, 2019). "Though p-values were <0.05 for some tag SNPs and haplotypes in VDR, CYP24A1, and RXRA prior to FDR adjustment, none of the SNPs or haplotypes were significantly associated with breast cancer risk after accounting for FDR." (PMID 26488576, 2015). "The levels of protein expression of CYP27B1 and CYP24A1 have not been previously studied in breast cancer." (PMID 20831823, 2010). "In the context of breast cancer, genes within the conserved signatures, such as those that characterize the more purified luminal progenitor subset (for example, KIT, CYP24A1, ELF5), have the potential to provide novel prognostic markers or therapeutic targets in breast cancer." (PMID 20346151, 2010).
vitamin D deficiency (39 papers, 2010 to 2025). A nutritional condition produced by a deficiency of VITAMIN D in the diet, insufficient production of vitamin D in the skin, inadequate absorption of vitamin D from the diet, or abnormal conversion of vitamin D to its bioactive metabolites. "The study concluded that genetic variation at several loci—rs2282679 in GC, rs12785878 near DHCR7, rs10741657 in CYP2R1, and rs6013897 in CYP24A1—have a noticeably elevated risk of vitamin D insufficiency." (PMID 36672957, 2023). "Given that the prevalence of pathogenic CYP24A1 mutations is very low and considering the beneficial effects of preventing and treating vitamin D deficiency, we do support the current recommendations for vitamin D intakes and supplementation." (PMID 35745247, 2022). "In contrast, the mRNA levels of Cyp24a1, which is responsible for the conversion of active 1,25(OH)2D into the inactive form, were significantly lower in the vitamin D-deficiency − UV irradiation group than in the other groups." (PMID 32681041, 2020). "Variants of GC (rs1155563) and CYP24A1 (rs6013897) were significantly associated with both 25(OH)D concentrations and vitamin D deficiency among pregnant women, respectively." (PMID 32884689, 2020). "One SNV (rs59128934) on VDR and another (rs3886163) on CYP24A1 were associated with increased risk to Vitamin D deficiency." (PMID 32834827, 2020). "Over expression of CYP24A1 enzyme is correlated with vitamin D deficiency and resistance to vitamin D therapy." (PMID 30286109, 2018). "DHCR7 and CYP24A1 have the largest reported effect sizes for Vitamin D deficiency and were found using ET." (PMID 27042214, 2016). "This is equivalent to 2.5 fold higher than vitamin D deficient females which had concentrations considered to be above normal given that CYP27B1 expression is increased whereas that for CYP24A1 is decreased under vitamin D deficiency." (PMID 23405058, 2013). "Other factors involved in CKD-derived vitamin D deficiency include resistance to vitamin D, reduced hepatic synthesis of CYP24A1, and upregulation of 24–25(OH)2D, which is a metabolite produced by increased action of the catabolic enzyme CYP24A1, which causes hydroxylation of 25 (OH)D." (PMID 41373702, 2025). "One study found that the upregulation of CYP24A1 expression decreased vitamin D, which is related to chronic kidney disease; therefore, blocking CYP24A1 activity might be an approach for correcting vitamin D deficiency in patients with chronic kidney disease." (PMID 37359004, 2023). "On the other hand, an unbalanced high expression of CYP24A1 may lead to vitamin D deficiency thereby causing various disorders connected to bone metabolism, immunomodulation and proliferative disorders like cancer." (PMID 37601072, 2023). "CYP24A1 encodes vitamin D 24-hydroxylase and is largely silent under vitamin D deficiency." (PMID 36139230, 2022). "Note induced CYP24A1 expression may provide a rational for the common observation of vitamin D deficiency in NAFLD patients." (PMID 30547786, 2018). "Although we did not quantify active vitamin D (calcitriol) or vitamin D metabolizing enzymes (e.g., CYP27B1, CYP24A1), a tissue-level functional vitamin D deficiency could still propagate circadian misalignment and destabilize the otoconial matrix despite normal systemic electrolytes." (PMID 41468411, 2025). "For this reason, we investigated the influence of 25 OH vitamin D deficiency and of SNPs in genes implicated in vitamin D metabolism (VDR and CYP24A1) on lipid parameters." (PMID 37632926, 2023). "In accordance to our findings, Zhu H. and colleagues revealed that participants with severe vitamin D deficiency (25(OH)D ≤25 nmol/l) showed a pattern of reduced methylation of CYP2R1, CYP24A1 and DHCR7 genes in comparison with controls (25(OH)D >75 nmol/L)." (PMID 36061943, 2022). "VMR relies primarily on CYP24A1 expression, which is downregulated in vitamin D deficiency; therefore, VMR is also expected to reduce in vitamin D deficiency." (PMID 33606762, 2021).
vitamin D deficiency (continued). "The associations of CYP2R1, CYP24A1, and CYP27B1 gene polymorphisms with vitamin D deficiency in multiple population have been reported." (PMID 34484304, 2021). "Moreover, individuals with polymorphisms in CYP24A1 (rs2248137) and LRP2 (rs2389557 and rs4667591), coupled with vitamin D deficiency in the second trimester, demonstrated an elevated risk of developing HDP." (PMID 38613027, 2024). "Different variants in the loci of the genes responsible for the synthesis, hydroxylation, and transport of vitamin D (such as DHCR7, CYP2R1, CYP24A1, and GC), as well as VDR gene polymorphisms may also be associated with the risk of vitamin D deficiency." (PMID 33330279, 2020). "While positive associations were found for 3 SNVs in VDR (rs59128934, rs7965274 and rs2853564), 2 SNVs in CYP24A1 (rs56229249 and rs34043203) and 2 in CYP2R1 (rs12794714 and rs10500804), indicating that the presence of such variations increase risk to vitamin D insufficiency." (PMID 32834827, 2020). "Vitamin D insufficiency was present in 62% and CYP24A1 was overexpressed in this group." (PMID 31179282, 2019). "Clinically, this ratio is a more reliable indicator of HCINF1 due to CYP24A1 mutations than serum 24,25(OH)2D3 alone because it eliminates the possibility that the patient might have a low serum 24,25(OH)2D3 level due to vitamin D deficiency." (PMID 35956396, 2022). "Different variants in the loci of genes (such as DHCR7, CYP2R1, CYP24A1, and GC) that are responsible for vitamin D synthesis, hydroxylation, and transport, as well as VDR gene polymorphisms, may be associated with the risk of vitamin D deficiency." (PMID 33330279, 2020). "To study the possible mechanisms whereby vitamin D deficiency worsens with increased severity of liver dysfunction, we measured hydroxylases protein levels of CYP2R1, CYP27A1 (key enzymes in vitamin D synthesis) and CYP24A1 (key enzyme in vitamin D degradation) in 94 out of 345 subjects." (PMID 27399065, 2016). "Importantly, the simultaneous measurement of 25(OH)D and 24,25(OH)2D3 as it was done in our study allows to improve the identification of individuals with vitamin D deficiency, CYP24A1 lack of function mutations, vitamin D intoxication or uncontrolled 1,25(OH)2D production in granulomatous diseases." (PMID 33825696, 2021).
lung carcinoma (36 papers, 2012 to 2025). "When smokers' CYP24A1 genes were affected by smoke, lower vitamin D levels were linked to lung cancer risk." (PMID 34646549, 2021). "We were especially interested in genetic variants in CYP24A1 due to its previously observed overexpression in lung and other tumor types and reported association with poorer lung cancer survival." (PMID 29726119, 2018). "We indeed observed that rs10623012 heterozygous and homozygous minor genotypes were inversely associated with lung cancer status, displayed a significant upward trend with vitamin D3 levels and were negatively associated with CYP24A1 mRNA expression." (PMID 29726119, 2018). "Of the 27 observed associations with lung cancer, 89% of the SNPs were located in CYP24A1 and VDR genes, and several of those SNPs were found to significantly modulate vitamin D3 levels." (PMID 29726119, 2018). "Regarding another CYP24A1 SNP, rs4809957, our finding suggests the variant genotype associated with increased risk of lung cancer." (PMID 25544771, 2015). "This disparity effect of the CYP24A1 variant in lung cancer susceptibility and SCLC survival is currently unknown." (PMID 25415319, 2014). "Although circ_0060927 expression in limited lung cancer samples is not pronounced higher in GEO datasets, the expression of its host gene CYP24A1 in lung cancer tissues is much higher both in GEO and TCGA datasets." (PMID 41323393, 2025). "This conclusion can aid better personalized medicine for lung cancer management, while further assessment for genetic variants of CYP3A4, CYP27B1, CYP24A1, GC, and VDR is still required to address more robust evidence." (PMID 38482381, 2024). "Previous research shows that overexpression of cytochrome P450 family 24 subfamilies A member 1 (CYP24A1) enhances lung cancer cell proliferation through activating RAS signaling." (PMID 36793588, 2023). "The authors reported that the CYP24A1 gene was the most highly expressed circular RNA identified in a lung cancer cell line, A549." (PMID 36672957, 2023). "The results of recent study also showed that the miR-17 to -92 cluster also control CYP24A1 expression in lung cancer cells." (PMID 34208589, 2021). "Eighty‐nine percent of the associated SNPs were located in CYP24A1 and VDR, indicating enrichment of genetic variation in the vitamin D signaling cascade associated with lung cancer in those pivotal genes." (PMID 29726119, 2018). "In this study, polymorphisms in 3′-untranslated region of IL-16, CYP24A1, and FBN1 were determined in 322 lung cancer patients and 384 healthy controls with the usage of Sequenom MassARRAY." (PMID 30671474, 2018). "We genotyped 296 SNPs in CYP2R1, CYP27A1, CYP27B1, CYP24A1, and VDR and observed associations between 27 SNPs and lung cancer status after the adjustment for age, gender, and race, all of which had passed the Hardy–Weinberg equilibrium assessment." (PMID 29726119, 2018). "Consistently, CYP24A1 expression is correlated with the advanced stages of colon, prostate, breast, and lung cancers, inducing resistance to vitamin D-based therapy." (PMID 29657326, 2018). "A number of clinical studies have indicated that CYP24A1 is overexpressed in lung cancer patients compared with normal control tissues." (PMID 27669215, 2016). "In lung cancers, elevated expression of CYP24A1 was more prominent in poorly differentiated tumors and was correlated with worse survival prognosis." (PMID 25334067, 2014). "Previous studies have shown that CYP24A1 is overexpressed in many types of human cancer including lung cancer and overexpression of this enzyme is an independent prognostic maker of survival in patients with lung adenocarcinoma." (PMID 25415319, 2014).
lung carcinoma (continued). "The most highly expressed circular RNA identified in our analysis was from the CYP24A1 gene, in a lung cancer cell line, A549." (PMID 24039610, 2013). "The oncogenic role of CYP24A1 was also shown in breast, prostate, and lung cancer." (PMID 37242266, 2023). "CYP24A1 overexpression is associated with accelerated cell growth and invasion and worse survival in LUAD, and its polymorphisms are associated with susceptibility to lung cancer." (PMID 36052170, 2022). "In addition, when PRI-2191 was combined with RESV, significant upregulation of CYP24A1 expression was noticed in some lung cancer cells, confirming the ability of RESV to modulate the action of vitamin D in these cells." (PMID 33652978, 2021). "Additionally, genotyping of 296 SNPs in the same subjects resulted in findings that 27 SNPs, predominantly in CYP24A1 and VDR genes, were significantly associated with lung cancer status, affected mRNA expression, and modulated vitamin D levels." (PMID 29726119, 2018). "Supporting the oncogenic role of CYP24A1, the inhibition of CYP24A1 suppressed tumor growth and potentiated the antitumorigenic effects of calcitriol in breast and lung cancers, suggesting that CYP24A1 could be a promising therapeutic target." (PMID 29657326, 2018). "Moreover, a recent study showed that the miR-17 to -92 cluster also regulates CYP24A1 expression in lung cancer cells." (PMID 29657326, 2018). "Also, a lung cancer cell line with high CYP24A1 expression was also more resistant to the antiproliferative action of vitamin D3 than cell lines with low CYP24A1 expression." (PMID 25334067, 2014). "On the other hand, we have previously shown that in lung cancer cells that were either sensitive or resistant to the antiproliferative activity of vitamin D, vitamin D signaling was active as revealed by the upregulated expression of CYP24A1 after treatment with vitamin D compounds." (PMID 33652978, 2021). "In addition to genes associated with smoking the AC1/AC2 classifier included several genes implicated in lung cancer tumorigenesis, such as KITID1MMP7MYCNXRN2, and CYP24A1, as well as type II pneumocyte marker genes such as NKX2-1 (TTF1/TITF1), LAMP3 (CD208), and surfactant proteins SFTPB and SFTPC." (PMID 22676229, 2012). "Our meta-analysis revealed the lack of association of CYP2R1 (rs10741657), CYP27B1 (rs3782130), CYP27B1 (rs10877012), CYP24A1 (rs6068816), CYP24A1 (rs4809960), CYP3A5 (rs776746), GC (rs7041), GC (rs4588), and VDR (ApaI: rs7975232) with lung cancer." (PMID 38482381, 2024). "For example, CYP24A1 has oncogenic properties in lung adenocarcinoma and AKR1B10 has been shown to induce the metastatic potential of lung cancer cells to the brain in vitro." (PMID 33255394, 2020). "Second, CYP24A1 rs4809957 was demonstrated to be only related to the TNM staging and lymph node metastasis of lung cancer in this work." (PMID 30671474, 2018). "We further genotyped 296 SNPs in the same subjects (N = 761) in CYP2R1, CYP27A1, CYP27B1, CYP24A1, and VDR genes directly involved in vitamin D metabolism, with an objective to elucidate variants that may modulate vitamin D levels, thereby potentially explaining their associations with lung cancer." (PMID 29726119, 2018). "Moreover, it has been shown that expression of the CYP24A1, CYP27B1, and VDR genes in lung cancer is affected by tumor differentiation and characterization." (PMID 36986255, 2023). "Thus far, we know that the genetic expression of CYP24A1, CYP27B1, and VDR in lung cancer is affected by tumor differentiation and characterization." (PMID 34836039, 2021). "KRAS-mutant lung cancer cells are refractory to 1,25(OH)2D3 due to perturbations in key determinants of vitamin D signaling, such as low levels of VDR and elevated expression of CYP24A1." (PMID 32183160, 2020).
lung carcinoma (continued). "There was no obvious evidence for rs859 related to lung squamous cell carcinoma risk, TNM staging, and lymph node metastasis; however, CYP24A1 rs4809957 appeared to be correlated with TNM staging and lymph node metastasis of lung cancer in different genetic models (P > 0.05)." (PMID 30671474, 2018). "Unfortunately, stratified results for gender and age on CYP24A1 rs4809957 and FBN1 rs1042078 did not uncover any associations of these SNPs with lung cancer susceptibility in Chinese Han population (P > 0.05)." (PMID 30671474, 2018). "Although we attempted to address this issue by analyzing publicly available GEO and TCGA datasets, where circ_0060927’s host gene CYP24A1 was consistently elevated in lung cancer samples, the absence of actual validation in patient remains a notable limitation." (PMID 41323393, 2025).